TET2 (tet methylcytosine dioxygenase 2)
Diseases named in the same sentence as TET2 in open-access papers (continued):
Sharing a sentence is not in itself a finding about the gene and the disease.
atherosclerosis (continued). "It has also been shown that TET2-mutation-associated clonal hematopoiesis accelerates the progression of atherosclerosis in mice, which is the pathological basis of thrombosis, indirectly reflecting the correlation between TET2 mutation and thrombosis." (PMID 36431092, 2022). "This positive feedback loop would be responsible for the pathogenesis of diabetes and atherosclerosis in TET2-mutated CHIP." (PMID 35657494, 2022). "Probably it is the cells of myeloid origin; most likely, macrophages mediate the acceleration of atherosclerosis with TET2 mutations." (PMID 35453534, 2022). "Mechanistically, deficiency of Tet2 in macrophages drives an increase in IL‐1β increasing the development of atherosclerosis in these mice." (PMID 35834102, 2022). "One study, however, has linked mutations in the epigenetic regulator Tet2 with atherosclerosis and heart disease—one of the most frequent diseases associated with ageing." (PMID 35834102, 2022). "In a similar article, it was also shown that Tet2-deficient macrophages accelerate the development of atherosclerosis and have pro-inflammatory properties, expressed in increased production of cytokines, including IL-1β." (PMID 35453534, 2022). "Studies using mouse models have found TET2 loss to be associated with elevated cytokines/chemokines, resulting in increased susceptibility to colitis and IL-1β dependent atherosclerosis." (PMID 35228982, 2022). "Being involved in the DNA demethylation process, TET2 facilitates the suppression of IL-6 and IL-1β, inflammatory mediators implicated in the pathogenesis of atherosclerosis." (PMID 35663390, 2022). "The heterozygosity for the TET2 mutation of the transplanted cells was sufficient to accelerate atherosclerosis, albeit to a lesser extent." (PMID 35453534, 2022). "In mice, TET2-deficient bone marrow-transplanted cells expanded in the blood and accelerated atherosclerosis." (PMID 34576030, 2021). "A causal link between somatic Tet2 mutation-induced clonal hematopoiesis and exacerbated atherosclerosis has been suggested." (PMID 34222235, 2021). "Subsequently, these findings have been replicated in other murine models of TET2 deficiency, confirming the association of TET2 deficiency in accelerated atherosclerosis through induction of a proinflammatory state." (PMID 33861346, 2021). "In a mouse model of low-density lipoprotein receptor deficiency, Tet2 loss of function preferentially resulted in the development of atherosclerosis." (PMID 34222235, 2021). "The association between IL-1β overproduction by TET2 mutation and increased atherosclerosis is supported by the results of the Canakinumab Anti-Inflammatory Thrombosis Outcomes Study (CANTOS) trial." (PMID 34576030, 2021). "Myeloid-specific TET2 ablation is sufficient to promote atherosclerosis, indicating that macrophages play a role in these TET2-deficient cells." (PMID 34576030, 2021). "Enhanced atherosclerosis with TET2 deficiency in macrophages is mediated through increasing proinflammatory signaling, including IL-1β, IL-6, and NOD-, LRR-, and the pyrin domain-containing protein 3 (NLRP3) inflammasome complex." (PMID 34576030, 2021). "Deficiency of DNA-demethylating enzyme TET methylcytosine dioxygenase 2 (TET2) in hematopoietic cells accelerates atherosclerosis by elevating expression of cytokines and chemokines and NLRP3 inflammasome activation." (PMID 34003795, 2021).
atherosclerosis (continued). "Experimental studies confirmed that genetic TET2 deficiency in murine hematopoietic stem cells promotes cardiac dysfunction and accelerates atherosclerosis in mice." (PMID 32948843, 2021). "Further studies revealed a causal link between TET2 mutations in hematopoietic stem cells, increased inflammation, and atherosclerosis." (PMID 33520997, 2020). "Our results are in accordance with recent evidence linking TET2 mutations with atherosclerosis and increased cardiovascular risk." (PMID 32290079, 2020). "Tet2-deficiency facilitates the upregulation of inflammatory cytokines (notably IL-1b) that contribute to the pathogenesis of atherosclerosis in mice." (PMID 31963585, 2020). "Somatic mutations of DNMT3A and TET2 were also associated with accelerated atherosclerosis, thus increasing the risk of cardiovascular disease mediated by inflammatory mechanisms." (PMID 32457355, 2020). "For example, a 2012 study showed that loss of TET2 function was associated with atherosclerosis and the increased secretion of pro-inflammatory factors including IL-1β." (PMID 32290079, 2020). "Competitive transfer of Tet2-deficient bone marrow cells resulted in enlarged atherosclerotic lesions in irradiated, atherosclerosis-prone mice that are deficient for low-density lipoprotein receptor (Ldrl−/−)." (PMID 33520997, 2020). "Based on these findings, synthetic SIRT1 activators or resveratrol, which is one of the potent natural compounds activating SIRT1, are reasonable candidates for mitigating deleterious effects of TET2 mutations on hematopoiesis, atherosclerosis, and CVD." (PMID 33114351, 2020). "The involvement of hematological TET2-deficiency in the pathogenesis of atherosclerosis has been investigated at the cellular level." (PMID 31963585, 2020). "In the context of TET2-mutation-positive CH, prophylactic treatment for atherosclerosis using cholesterol-lowering medications or compounds targeting IL-1β and other inflammatory pathways as proposed would, if effective, be a significant advance." (PMID 30890702, 2019). "Heterozygous and homozygous Tet2 loss in mice accelerates atherosclerosis, possibly via enhanced macrophage-driven inflammation." (PMID 30890702, 2019). "The proposed mechanism for the link between clonal hematopoiesis and atherosclerosis involves increased NLRP3 inflammasome-mediated IL1β secretion in TET2-deficient macrophages in mice." (PMID 31712595, 2019). "Mechanistically, exacerbated IL-1β secretion by macrophages was proposed to be essential for accelerated atherosclerosis in context of CH due to Tet2 loss in mice." (PMID 30890702, 2019). "An anterior study reported TET2 somatic mutations in blood cells play a causal role in atherosclerosis and partial bone marrow reconstitution with TET2-deficient cells led to a marked increase in atherosclerotic plaque size." (PMID 31123222, 2019). "Considering these, CVD burden in the Finnish mutation carriers was unremarkable, and we were unable to derive significant clinical evidence for a role of TET2 germline mutation positivity in predisposition to atherosclerosis." (PMID 30890702, 2019). "Other experiments are required to elucidate the exact molecular mechanisms underlying TET2 effects and its roles in signal transduction pathways, which will be clinically targeted for the prevention or treatment of atherosclerosis." (PMID 27821816, 2016). "TET2-deficient macrophages are highly pro-inflammatory, and this state accelerates atherosclerosis, as demonstrated in mouse models with increased atherosclerotic plaque burden and promotion of myocardial fibrosis, HF, and worsened cardiac outcomes in response to stress." (PMID 39997650, 2025). "The loss of TET2 in hematopoietic stem cells (HSCs) was shown to disrupt DNA methylation patterns, thereby influencing hematopoietic cell clonality and promoting inflammatory processes that accelerate atherosclerosis." (PMID 40244103, 2025).
atherosclerosis (continued). "Concurrently, the discovery of the role of miR-33a/b in dyslipidemia (2011) and the identification of TET2 deficiency in accelerating atherosclerosis (2017) have highlighted the coordinated involvement of multiple epigenetic mechanisms in cardiovascular disease." (PMID 40428388, 2025). "Specifically, patients harboring a TET2 mutation or experiencing a loss of TET2 functionality are predisposed to an elevated risk of developing various cardiovascular pathologies, such as atherosclerosis, pulmonary hypertension, aortic valve stenosis, and heart failure." (PMID 40067382, 2025). "In mouse models, TET2 deficiency in bone marrow accelerates atherosclerosis." (PMID 41516113, 2025). "In addition, it is known in experimental models that myeloid TET2 deficiency is associated with increased IL-1β production, and with enhanced atherosclerosis development." (PMID 39515317, 2024). "In recent years, there has been a growing interest in CHIP due to TET-2 loss of function variants because preclinical studies have suggested that Tet2 loss of function in myeloid cells, and the subsequent increase in IL-1 β-related signaling, act as accelerators of atherosclerosis." (PMID 38673815, 2024). "Finally, while TET2 mutations promote inflammation and atherosclerosis in mouse models, mLOY was shown to switch macrophages from a pro-inflammatory to a pro-fibrotic phenotype." (PMID 39665621, 2024). "In humans, CHIP due to DNMT3A shows a weaker association with atherosclerosis than TET2." (PMID 39352379, 2024). "Clone results of bone marrow cells with TET2 mutation showed IL-6 and IL-1 β, which may lead to accelerated atherosclerosis." (PMID 37361203, 2023). "Mutations in DNMT3A and TET2 account for approximately 50% of CHIP mutations in people with atherosclerosis, with somatic DNMT3A mutations accounting for roughly 35% of mutations in patients with CHIP and coronary artery disease and early-onset myocardial infarction." (PMID 37947606, 2023). "Moreover, RNA sequencing of cells with loss-of-function mutations in TET2 showed augmented expression of pro-inflammatory mediators implicated in the pathogenesis of atherosclerosis including IL-1β and IL-6." (PMID 35657494, 2022). "The difference in aortic plaque size between the Tet2-deficient mice and control mice was abrogated by use of an NLRP3 inhibitor, identifying a key role for NLRP3-mediated IL-1β overproduction in promoting atherosclerosis in those harboring TET2 CHIP mutations." (PMID 35122117, 2022). "In addition, some studies showed that TET-2 was an important negative transcriptional suppressor of proinflammatory responses, and TET-2 function was associated with atherosclerosis development in mice through enhanced inflammatory responses." (PMID 35965615, 2022). "In particular, mutations of TET2 are associated with inflammation and atherosclerosis." (PMID 35663390, 2022). "Moreover, mutations in the TET2 that can promote clonal hematopoiesis were associated with an increased risk of atherosclerosis." (PMID 34301176, 2021). "Tet2-deficiency in myeloid cells was found to independently accelerate atherogenesis in mice and highlighted a potential role of Tet2-deficient macrophages as agents of atherosclerosis." (PMID 31963585, 2020). "It seems possible, therefore, that for the development of hematopoietic clones with somatic mutations, TET2 could, similar to what occurs in atherosclerosis, constitute a risk factor for the development of aortic valve stenosis." (PMID 32640513, 2020).
atherosclerosis (continued). "As one of the hotspots mutated genes in the peripheral blood mononuclear cells (PMBCs) of the elderly population, which was also known as clonal hematopoiesis of indeterminate potential (CHIP), TET2 mutation is associated with an increased risk for atherosclerosis and cardiac diseases." (PMID 32616016, 2020). "Our data raise the possibility, that circulating TET2-mutant cells may be of limited importance as an atherosclerosis risk factor, at least in the context of germline mutation where all cell types carry the mutation." (PMID 30890702, 2019). "Furthermore, CHIP could contribute to chronic inflammation; for example, loss of ten eleven translocation-2 (TET2) upregulated inflammatory mediators, such as interleukin-6, in mouse colitis and mouse atherosclerosis models." (PMID 36864496, 2023). "In experimental analysis, it could be further shown that clonal hematopoiesis associated with TET2 deficiency leads to accelerated atherosclerosis mainly driven by interactions between clonal monocytes-macrophages and the endothelium and an increased expression of pro-inflammatory genes." (PMID 35657494, 2022). "Furthermore, augmented IL-1β and NLRP3-inflammasome activation was described as a major driver of atherosclerosis in mice with hematopoietic Tet2 deficiency, and pharmacologic inhibition of the inflammasome significantly reduced the proatherogenic effect of Tet2-deficient myeloid cells." (PMID 32825226, 2020). "The authors demonstrated that TET2 loss of function in macrophages exacerbated NLR Family Pyrin Domain Containing 3 (Nlrp3) mediated Interleukin 1 beta (IL-1b) production which in turn accelerated atherosclerosis in a context of CHIP, thereby demonstrating that CHIP leads to increased inflammation." (PMID 32526214, 2020). "Therefore, the loss of TET2 might result in vulnerable plaque formation, and TET2 upregulation may be beneficial to prevent atherosclerosis." (PMID 27821816, 2016). "However, whether TET2 dysregulation is directly implicated in the initiation and progression of atherosclerosis remains to be determined." (PMID 27821816, 2016). "We selected 26 TET2 CHIP CAD mutation carriers for CHIP detection in left ventricular myocardium and atherosclerosis-affected carotid and coronary artery samples." (PMID 40900105, 2026). "Experimental atherosclerosis was increased in females with Tet2 and males with Jak2, but it was unchanged with Dnmt3a mutations." (PMID 41433101, 2025). "In seminal studies involving TET2 deficiency, CHIP-associated MASH, atherosclerosis, and cardiac arrhythmias, an unconstrained inflammatory response from TET2-deficient macrophages has been implicated in disease pathophysiology." (PMID 40794443, 2025). "Preclinical studies have shown that macrophages deficient in TET2 or DNMT3A drive interleukin (IL)-1β/IL-6 inflammasome activation, thereby promoting atherosclerosis and metabolic dysfunction, whereas the JAK2V617F mutation accelerates thrombosis." (PMID 41516113, 2025). "For instance, mice with TET2 knockout bone marrow transplants showed accelerated atherosclerosis, activated through the NLRP-3/IL-1β inflammasome pathway and upstream IL-6 signaling." (PMID 40355940, 2025). "DNA demethylation, mediated by enzymes such as TET2, plays an equally critical role in atherosclerosis." (PMID 40076813, 2025). "In diabetes, reduced 5 hmC levels and diminished TET2 activity in circulating leukocytes have been observed, contributing to increased myelopoiesis, atherogenic monocyte production, and accelerated atherosclerosis." (PMID 40076813, 2025). "TET2 deletion promotes the occurrence of cardiovascular disorders such as cardiac failure and atherosclerosis by the activation of IL‐1β/NLRP3 inflammasome through macrophages." (PMID 40607626, 2025).
atherosclerosis (continued). "In mice, Tet2 loss-of-function results in upregulation of inflammatory cytokines including IL-6, TNF-α, and IL-1β due to impaired intestinal barriers, and Tet2−/− mice display increased rates of atherosclerosis and colitis compared to wildtype (WT) animals." (PMID 39626264, 2025). "Over time, Tet2−/− cells gradually expanded with a slight skewing towards the myeloid lineage, leading to the progression of atherosclerosis and increased plaque size." (PMID 39119355, 2024). "TET2 LOF appears to promote atherosclerosis primarily via enhanced transcription and NLRP3-mediated posttranslational processing of the inflammatory cytokine IL-1β." (PMID 39352379, 2024). "Specifically, it has been found that hematopoietic mutations in common driver genes, DNMT3A, TET2, and JAK2V671F, can accelerate experimental atherosclerosis and/or heart failure by generating a pool of myeloid cells with an augmented proinflammatory profile." (PMID 36414855, 2023). "DNA demethylating enzyme TET2 represses the upregulation of pro-inflammatory cytokines, chemokine, and inflammasome activation, thus preventing atherosclerosis." (PMID 38031118, 2023). "Multiple studies have proven that the deletion of one copy of the Tet2 gene is adequate to an increase atherosclerosis occurrence in mice." (PMID 37686238, 2023). "Recently, it was demonstrated that TET2 ameliorated atherosclerosis progression in ApoE−/− mice via modulating Beclin1-dependent autophagic processes." (PMID 38031118, 2023). "DNMT-dependent changes in EC DNA methylation, associated with disturbed flow and endothelial inflammation, have been shown in vitro and in animal models in vivo and a role for EC-expressed TET2 in atherosclerosis progression has been demonstrated in mice." (PMID 37304954, 2023). "EVs from endothelial cells subjected to a proinflammatory stimulus have a lower amount of TET2, which, after transfer to vascular SMCs, promotes a change in their phenotype leading to the formation of atheroma plaque and the development of atherosclerosis." (PMID 35495944, 2022). "Amelioration of atherosclerosis and HF in Tet2 depleted mice by pharmacological inhibition of the NLRP3 inflammasome (MCC950), followed by reduction of IL-1b further confirmed this functional concept." (PMID 36355225, 2022). "Second, it was dependent on the identity of the affected gene with mutations in JAK2 leading to a 12-fold increase, whereas mutations in the most frequently affected genes TET2 and DNMT3A conferred a two-fold increase in the risk of developing atherosclerosis." (PMID 36355225, 2022). "In mouse models, Tet2 deletion accelerates atherosclerosis through enhanced secretion of cytokines, i.e., Il-8 and Il-1β30,65 whereas Mif deletion reduces the aortic inflammatory response." (PMID 35115654, 2022). "The expansion of the ten-eleven-translocation-2 (TET2) mutant hematopoietic clones is suggested to be an important driver of atherosclerosis." (PMID 36613465, 2022). "Some reports have demonstrated that Tet2 acts as an important factor during the development of atherosclerosis." (PMID 34222235, 2021). "Mechanistically, the majority of published studies focused on the effect of TET2 loss, while the role of DNMT3A or ASXL1 mutations in the myeloid compartment on the development of atherosclerosis is not well understood." (PMID 32825226, 2020). "In a previous study, regarding the involvement of TET2 in cardiovascular disease, TET2 knockouts presented increased macrophage inflammatory activation, accelerating atherosclerosis." (PMID 32849788, 2020). "Mice that lack Tet2 have accelerated atherosclerosis and a heightened tendency to develop left ventricular dysfunction." (PMID 32748835, 2020). "In this context, Jaiswal and colleagues showed that, when atherosclerosis prone mice were transplanted with Tet2 knockout bone marrow cells, the development of atherosclerosis was markedly accelerated on the background of a high cholesterol, high-fat diet." (PMID 32526214, 2020).